RNU6-45P (RNA, U6 small nuclear 45, pseudogene)
Synonyms: RNU6-45
Gene: Small nuclear RNA gene on chromosome 11 (63,970,470 to 63,970,576, forward strand). Ensembl gene ENSG00000207200.
Homologues: Orthologues: chimpanzee U6 (98% identical), rat U6 (93% identical), dog U6 (90% identical), pig U6 (81% identical). Paralogues in human: RNU6-12P (97% identical), RNU6-13P (97% identical), RNU6-32P (97% identical), RNU6-1 (96% identical), RNU6-17P (96% identical), RNU6-18P (96% identical), RNU6-2 (96% identical), RNU6-39P (96% identical), RNU6-3P (96% identical), RNU6-4P (96% identical), RNU6-5P (96% identical), RNU6-6P (96% identical), and 1289 more.